GABRR1 (gamma-aminobutyric acid type A receptor subunit rho1)
Description:
Rho subunit of the pentameric ligand-gated chloride channels responsible for mediating the effects of gamma-aminobutyric acid (GABA), the major inhibitory neurotransmitter in the brain. Rho-containing GABA-gated chloride channels are a subclass of GABA(A) receptors (GABAARs) entirely composed of rho subunits, where GABA molecules bind at the rho intersubunit interfaces. When activated by GABA, rho-GABAARs selectively allow the flow of chloride anions across the cell membrane down their electrochemical gradient. Rho-1 subunits are primarily expressed in retina where rho-1-containing GABAARs may play a role in retinal neurotransmission. Rho-1 GABAARs are also involved in neuronal tonic (extrasynaptic) and phasic (synaptic) transmission in the Purkinje neurons of the cerebellum (By similarity). Rho-1 GABAARs may also contribute to the regulation of glial development in the cerebellum by controlling extrasynaptic transmission (By similarity).
Tractability: Small molecule: a structure with a bound ligand is known; a high-quality ligand is known; it belongs to a druggable protein family. Antibody: UniProt places it where antibodies can reach, with high confidence; its Gene Ontology location is reachable by antibodies, with high confidence; UniProt predicts a signal peptide or a membrane-spanning region. PROTAC: a small molecule that binds it is known.
Target class: Ion channel; GABA-A receptor; Ligand-gated ion channel
Gene: Protein-coding gene on chromosome 6 (89,177,504 to 89,231,278, reverse strand). Ensembl gene ENSG00000146276.
Subcellular location: Postsynaptic cell membrane; Cell membrane
Pathways (Reactome):
Neuronal System: GABA receptor activation
Gene Ontology:
Molecular function: GABA-A receptor activity; GABA-gated chloride ion channel activity; extracellular ligand-gated monoatomic ion channel activity; GABA receptor activity; identical protein binding; ligand-gated monoatomic ion channel activity involved in regulation of presynaptic membrane potential; monoatomic ion channel activity; protein domain specific binding; protein-containing complex binding; transmembrane signaling receptor activity
Biological process: chemical synaptic transmission; chloride transmembrane transport; gamma-aminobutyric acid signaling pathway; synaptic transmission, GABAergic; modulation of chemical synaptic transmission; monoatomic ion transmembrane transport; monoatomic ion transport; regulation of presynaptic membrane potential
Cellular component: plasma membrane; GABA-A receptor complex; GABA-ergic synapse; postsynaptic membrane; glutamatergic synapse; intracellular vesicle; membrane; presynaptic membrane
Genetic constraint (gnomAD): Loss-of-function variants: 47 observed, 50.13 expected, observed/expected ratio (o/e) 0.94, 90% interval 0.74 to 1.2. The upper end of that interval is the gene's LOEUF score, 1.2, which puts it in group 5 of 6, group 1 being the genes least tolerant of losing a copy. Missense variants: 571 observed, 610.39 expected, observed/expected ratio (o/e) 0.94, 90% interval 0.87 to 1. Synonymous variants: 203 observed, 226.76 expected, observed/expected ratio (o/e) 0.9, 90% interval 0.8 to 1.01.
Homologues: Orthologues: chimpanzee GABRR1 (99% identical), macaque GABRR1 (99% identical), guinea pig GABRR1 (96% identical), rabbit GABRR1 (95% identical), rat Gabrr1 (94% identical), mouse Gabrr1 (94% identical), pig GABRR1 (91% identical), tropical clawed frog gabrr1 (85% identical), zebrafish GABRR1 (74% identical), zebrafish gabrr1 (70% identical). Paralogues in human: GABRR2 (70% identical), GABRR3 (59% identical), GABRB3 (37% identical), GABRB2 (37% identical), GABRB1 (37% identical), GLRA3 (33% identical), GLRA2 (32% identical), GLRA1 (32% identical), GABRG1 (31% identical), GABRD (30% identical), GABRA6 (30% identical), GABRP (30% identical), and 33 more.
Diseases named in the same sentence as GABRR1 in open-access papers:
GABRR1 is named in the same sentence as 19 diseases in open-access papers, as found by Europe PMC text mining. Sharing a sentence is not in itself a finding about the gene and the disease. The quoted sentences say what the papers report.
Anxiety (2 papers, 2016 to 2021). Intense feelings of nervousness, tension, or panic often arise in response to interpersonal stresses. "Gabrr1 and Cysltr1 has few previous studies related to anxiety and depression." (PMID 34276303, 2021). "Significant associations were noted for four SNPs in the GABRR1 gene and one SNP in the NOTCH1 gene when comparing the ‘No symptoms' to the ‘Anxiety only' group." (PMID 27959334, 2016).
myopia (2 papers, 2016 to 2018). "Further studies are needed to investigate the effect of genetic deletion of GABRR1 on refractive eye development and the role of the GABAergic pathway in myopia development using gene knockout mice." (PMID 27020472, 2016). "Among the novel loci, GABRR1 on chromosome 6q15 (53 kb), encoding GABAC receptor subunit ρ1, is an interesting functional candidate suggestive of a role in myopia development." (PMID 27020472, 2016).
alcohol dependence (1 paper, 2014). Physical and psychological dependence on alcohol. "Ultimately, GABAA ρ receptors may play a role in several in vivo effects, including ethanol intake, that are relevant for alcoholism and may explain the association of polymorphisms linked with human GABRR1 and GABRR2 genes and alcohol dependence." (PMID 24454882, 2014).
alcohol use disorder (1 paper, 2019). "Interestingly, genetic deletion of GABRR1 potentiated sedative motor effects of ethanol in mice and SNPs in GABRR1 and GABRR2 genes are associated with alcohol use disorder." (PMID 31717954, 2019).
breast carcinoma (1 paper, 2017). "Twenty of the 27 common genes have published data presenting that these genes were associated with breast cancer, but seven genes (DUSP10, GABRA6, GABRR1, KIF21B, KLHL24, MAP2K2, and SLC10A1) might be passenger genes or have not yet been studied regarding their pathological roles in breast cancer." (PMID 28973975, 2017).
colon cancer (1 paper, 2019). "Further analysis via bioinformatics methods reported that high expression of GABRR1 showed a significant correlation with reduced overall survival rates, suggesting the crucial role of GABRR1 in the progression of colon cancer." (PMID 31921812, 2019). "A recent study has shown that GABRR1 is significantly upregulated by the transcriptome of chemokine (C-X-C motif) ligand 1-(CXCL1) treated colon cancer cells." (PMID 31921812, 2019).
diabetic (1 paper, 2015). "Previous studies in China have demonstrated association between polymorphisms at GABRR1 and diabetic cataract." (PMID 25760438, 2015).
medullary thyroid carcinoma (1 paper, 2019). "In addition, another research reported the upregulation of GABRR1 in cancer cohorts compared with the controls with regard to gene expression profiles of medullary thyroid carcinoma." (PMID 31921812, 2019).
neuroblastoma (1 paper, 2022). Neuroblastoma (NB) is the most common solid, extracranial childhood tumor. "Knockdown of LINC00622 in EVs reduced tumor growth in nude mice injected with neuroblastoma cells possibly by regulating the expression of gamma-aminobutyric acid type A receptor subunit rho1 (GABRR1) via the androgen receptor (AR)." (PMID 35202087, 2022).
schizoaffective disorder (1 paper, 2013). "PRKG1 also interacts with RGS2 and GABRR1, which have shown modest association with schizophrenia symptoms and schizoaffective disorder, respectively." (PMID 23922650, 2013).
GABRR1 also shares sentences with these, for which no sentence is quoted: depression (2 papers); alcoholism (1); autism (1); cancer (1); Cognitive impairment (1); epilepsy (1); neurodevelopmental disorder (1); schizophrenia (1); tumor (1).